CAPN9 (calpain 9)
Description:
Calcium-regulated non-lysosomal thiol-protease.
Synonyms: nCL-4; GC36
Tractability: Small molecule: a high-quality ligand is known. PROTAC: a small molecule that binds it is known.
Target class: Enzyme; Hydrolase
Gene: Protein-coding gene on chromosome 1 (230,747,348 to 230,804,397, forward strand). Ensembl gene ENSG00000135773.
Subcellular location (Human Protein Atlas): Vesicles; Golgi apparatus
Pathways (Reactome):
Extracellular matrix organization: Degradation of the extracellular matrix
Gene Ontology:
Molecular function: calcium ion binding; calcium-dependent cysteine-type endopeptidase activity
Biological process: digestion; proteolysis
Cellular component: cytoplasm
Genetic constraint (gnomAD): Loss-of-function variants: 65 observed, 77.11 expected, observed/expected ratio (o/e) 0.84, 90% interval 0.69 to 1.04. The upper end of that interval is the gene's LOEUF score, 1.04, which puts it in group 4 of 6, group 1 being the genes least tolerant of losing a copy. Missense variants: 767 observed, 817.59 expected, observed/expected ratio (o/e) 0.94, 90% interval 0.88 to 1. Synonymous variants: 272 observed, 310.13 expected, observed/expected ratio (o/e) 0.88, 90% interval 0.79 to 0.97.
Homologues: Orthologues: chimpanzee CAPN9 (99% identical), macaque CAPN9 (98% identical), dog CAPN9 (92% identical), pig CAPN9 (90% identical), rabbit CAPN9 (88% identical), guinea pig CAPN9 (86% identical), mouse Capn9 (86% identical), rat Capn9 (86% identical), tropical clawed frog capn9 (70% identical), zebrafish capn9 (62% identical), Drosophila melanogaster CalpA (47% identical), Caenorhabditis elegans clp-1 (35% identical), and 6 more. Paralogues in human: CAPN3 (55% identical), CAPN1 (53% identical), CAPN2 (50% identical), CAPN8 (49% identical), CAPN11 (48% identical), CAPN12 (40% identical), CAPN14 (37% identical), CAPN5 (29% identical), CAPN13 (29% identical), CAPN6 (27% identical), CAPN10 (24% identical), CAPN7 (22% identical), and 8 more.
Diseases named in the same sentence as CAPN9 in open-access papers:
CAPN9 is named in the same sentence as 14 diseases in open-access papers, as found by Europe PMC text mining. Sharing a sentence is not in itself a finding about the gene and the disease. The quoted sentences say what the papers report.
gastric cancer (10 papers, 2010 to 2021). A primary or metastatic malignant neoplasm involving the stomach. "Further adjustment of covariate factors using multivariate Cox analysis identified T stage (P = 0.031), lymph node metastasis (P = 0.023) and calpain-9 expression (P = 0.003) as independent risk factors for gastric cancer." (PMID 27404891, 2016). "Vessel invasion (P < 0.001), T stage (P < 0.001), lymph node metastasis (P < 0.001), distant metastasis (P = 0.046), TNM stage (P < 0.001), and calpain-9 expression (P < 0.001) were found to be risk factors for survival in patients with gastric cancer." (PMID 27404891, 2016). "In contrast to calpain-1 and calpain-2 isoforms, the downregulation of calpain-9 expression was associated with metastasis in patients with gastric cancer, suggesting the protective effect of calpain-9 expression and its roles in hampering gastric cancer progression." (PMID 33430230, 2021). "Since EBV is known to be implicated in gastric cancer, splicing modification could be another way of diminishing the level of CAPN9 protein, but at the post-transcriptional level." (PMID 30832682, 2019). "Consequently, our results demonstrated that expression of calpain-9 was decreased in gastric cancer and was associated with the prognosis of patients in gastric cancer." (PMID 27404891, 2016). "In addition, lost‐of‐function variants in CAPN9 might promote tumor formation, as Calpain‐9 induces cell cycle arrest and apoptosis, and low expression predicts a poorer prognosis in gastric cancer patients." (PMID 32615015, 2020). "Results indicated that by comparing with GES-1 cell line, the expression of calpain-9 at the mRNA and protein levels was significantly decreased in all gastric cancer cell lines." (PMID 27404891, 2016). "In conclusion, calpain-9 is a tumor suppressor that can be regarded as a potential prognosis indicator for clinical outcomes in gastric cancer." (PMID 27404891, 2016). "Western blot analysis revealed that calpain-9 protein levels were down-regulated in gastric cancer compared with matched adjacent normal gastric mucosa, while calpain-8 protein levels were not significantly altered." (PMID 27404891, 2016). "We next determined the effects of calpain-8 and calpain-9 on cellular apoptosis in gastric cancer cells." (PMID 27404891, 2016). "We next investigated the protein expression of calpain-8 and calpain-9 in 22 paired gastric cancer samples." (PMID 27404891, 2016). "Cell cycle analysis showed that G1 phase arrest in calpain-9-overexpressed gastric cancer cells was blocked in the presence of Z-ATAD-FMK." (PMID 27404891, 2016). "In both the TNM I+II and TNM III+IV subgroups, calpain-9 expression showed statistically significant value in predicting the outcomes of gastric cancer patients." (PMID 27404891, 2016). "Herein, we demonstrated that calpain-9 was generally decreased in gastric cancer cell lines and primary tumor tissues, while calpain-8 expression was not significantly altered." (PMID 27404891, 2016). "The results demonstrated that high expression of calpain-9 in tumor tissues showed a survival benefit in gastric cancer patients." (PMID 27404891, 2016). "Nevertheless, our previous data indicated that “the expression of calpain-9 was down-regulated in gastric cancer, and high calpain-9 expression oppositely predicted favorable prognosis in patient with gastric cancer”." (PMID 27689993, 2016). "In this study, we examined the potential effects of calpain-8 and calpain-9 on tumor growth in vitro and in vivo, and we also determined the clinical significance of calpain-9 expression as well as its correlation with gastric cancer progression." (PMID 27404891, 2016). "CCK-8 assay revealed that cell viability was reduced in calpain-9-transfected gastric cancer cells, while calpain-8 overexpression had little effect on cell viability." (PMID 27404891, 2016).
gastric cancer (continued). "To establish a more sensitive model for predicting the outcomes of patients with gastric cancer, we combined calpain-9 expression and TNM stage to create a prognostic score system." (PMID 27404891, 2016). "Calpain 9 expression is decreased in gastric cancer, deletion of CAPN9 gene encoding calpain 9 promotes the onset of malignant fibroblasts in culture, and CAPN10 gene is involved in digestive and laryngeal cancers." (PMID 23565252, 2013). "Gene expression of CAPN9 has turned out to be lowered in gastric cancer." (PMID 34238324, 2021). "For example, the calpain CAPN9 was showed to be downregulated in gastric cancer, leading to the hypothesis that this protein may act as a tumor suppressor." (PMID 30832682, 2019). "In addition, CAPN9 and CALN1 are thought to be associated with gastric cancer and schizophrenia (Schizophrenia Psychiatric Genome-Wide Association Study (GWAS) Consortium, 2011), respectively." (PMID 30693022, 2018). "In addition, calpain-9 could create a better predictive model for the outcomes of gastric cancer patients in the combination with TNM stage." (PMID 27404891, 2016). "Though the mechanisms underlying the decreased expression of calpain-9 in gastric cancer remains to be defined, these data suggest that other pathways rather than calpain-9 may be involved in the tumorigenic effect of calpain-4." (PMID 27689993, 2016). "Therefore, activation of caspase-12 might contribute to both G1/S phase block and apoptosis mediated by calpain-9 in gastric cancer." (PMID 27404891, 2016). "We also examined the expression of calpain-8 and calpain-9 in normalized gastric mucosa cell line GES-1 and various gastric cancer cell lines (AGS, MGC80-3, BGC-823, HGC-27, MKN-28, MKN-45, and SGC-7901)." (PMID 27404891, 2016). "To understand whether calpain-8 and calpain-9 were involved in gastric carcinogenesis, we first screened differentially expressed genes and examined the mRNA expression patterns of calpain family in gastric cancer tissues from reported GEO13 and TCGA-STAD14 datasets." (PMID 27404891, 2016). "Immunohistochemical (IHC) assay also confirmed that the protein expression of calpain-9, but not calpain-8, was decreased in gastric cancer samples." (PMID 27404891, 2016). "Annexin V staining revealed that overexpression of calpain-9, but not calpain-8, significantly increased cell apoptosis in both gastric cancer cell lines." (PMID 27404891, 2016). "Western blot analysis revealed that transfection with calpain-9, but not calpain-8, enhanced the cleavage of caspase-12 in both gastric cancer cell lines." (PMID 27404891, 2016). "Calpain-9 expression was apparently lower in gastric cancer tissues than in non-tumor gastric mucosa." (PMID 27404891, 2016). "Because calpain-9, but not calpain-8, was decreased in gastric cancer and displayed anti-tumorigenic effects in vitro and in vivo, we next determined the correlations between calpain-9 expression and clinicopathological features in 151 gastric cancer samples." (PMID 27404891, 2016). "However, unlike other members of the calpain family, we found that calpain-9 was down-regulated in gastric cancer in our study." (PMID 27404891, 2016).
breast carcinoma (3 papers, 2014 to 2017). "Low CAPN9 expression has been associated with poorer clinical outcome in breast cancer patients following endocrine therapy." (PMID 28341962, 2017). "An interesting observation of this study is that low calpain-9 expression is associated with disease-specific survival, whereas high expression of calpain-1 and calpain-2 are associated with poor breast cancer prognosis in other studies." (PMID 25539577, 2014). "This study suggests that calpain-9 may play a role in breast cancer and that low expression is associated with poorer patient clinical outcome following endocrine therapy." (PMID 25539577, 2014). "Interestingly, low calpain-9 expression was associated with adverse survival in breast cancer patients treated with endocrine therapy, whereas low expression of calpain-9 was associated with markers of good prognosis in the total patient cohort." (PMID 25539577, 2014). "There are few studies on calpain-9 and its activity and expression in breast cancer; however, in the breast cancer cell line MCF-7, calpain-9 appears to have a role in lumen formation." (PMID 25539577, 2014). "We investigated the expression of calpain-9 in a large cohort of early stage breast cancer patients (n = 783) using immunohistochemistry on a tissue microarray." (PMID 25539577, 2014). "We therefore assessed the expression of calpain-9 in breast cancer patients that received endocrine therapy against their clinicopathological data." (PMID 25539577, 2014). "This study aimed to investigate the expression of calpain-9 in breast cancer and to determine links with pathological variables of tumours and patient prognosis; in particular we aimed to investigate the importance of calpain-9 in patient subgroups including those that received endocrine therapy." (PMID 25539577, 2014). "As part of future research, these results require validation in multi-centre cohorts of breast cancer patients to determine the clinical utility of measuring calpain-9 expression as an indicator of response to endocrine therapy or in those patients with an intermediate NPI value." (PMID 25539577, 2014). "The expression of calpain-9 in breast cancer has been described in-vitro; however, this study clearly demonstrates that calpain-9 is expressed in invasive breast cancer and is not expressed solely in a digestive tract specific manner." (PMID 25539577, 2014).
serous ovarian cancer (3 papers, 2021 to 2025). "MiR-585-3p inhibits the proliferation and migration of high-grade serous ovarian cancer cells by targeting CAPN9." (PMID 40426913, 2025). "The study found that for high-grade serous ovarian cancer (HGSOC), CAPN9 may be a therapeutic target." (PMID 37007021, 2023).
gastropathies (1 paper, 2010). "Our results also identify CAPN8 and CAPN9 as promising targets for various stress-induced human gastropathies." (PMID 20686710, 2010). "Here we report that two gastrointestinal-tract-specific calpains, calpain 8/nCL-2 and calpain 9/nCL-4, are involved in the mucosal defense against stress-induced gastropathies." (PMID 20686710, 2010).
Hypertension (1 paper, 2025). The presence of chronic increased pressure in the systemic arterial system. "CAPN9 is expressed mainly in the stomach and small intestine and is involved in the regulation of hypertension, heart disease and gastric mucosal defense." (PMID 40426913, 2025).
invasive breast carcinoma (1 paper, 2014). A carcinoma that infiltrates the breast parenchyma. "This study investigated the expression of the calpain family member calpain-9 in a large consecutive series of early invasive breast cancer specimens using immunohistochemistry." (PMID 25539577, 2014).
lymph node metastasis (1 paper, 2016). "Low expression of calpain-9 was positively associated with male sex, late T stage, lymph node metastasis, and advanced TNM stage." (PMID 27404891, 2016). "Among the variables, low expression of calpain-9 was positively associated with male sex, late T stage, lymph node metastasis, and advanced TNM stage." (PMID 27404891, 2016).
type 2 diabetes (1 paper, 2023). "We also identified the CAPN9 gene, which contains type 2 diabetes SNPs and belongs to the Calpain family of genes, which have been linked to type 2 diabetes when overexpressed by impairing insulin exocytosis in beta cells." (PMID 37311878, 2023).
tumor (8 papers, 2014 to 2023). "Low expression of calpain-9 was associated with patients over 40 years, smaller tumour size and stage, favourable NPI values, and ER positive tumours." (PMID 25539577, 2014). "Low expression of calpain-9 was associated with patients over 40 years of age (P = 0.025), smaller tumour size (P = 0.001), lower tumour stage (P = 0.009), a more favourable Nottingham Prognostic Index value (P = 0.002) and positive oestrogen receptor status (P = 0.014)." (PMID 25539577, 2014). "By binding to the 3′-untranslated region (UTR) of CAPN9, tumor suppressor miR-585-3p inhibits the expression of CAPN9 to suppress the growth and migration of HGSOC." (PMID 37007021, 2023). "In this study, CAPN9 was expressed at significantly higher levels in tumor tissues and cell lines than in normal ovarian tissue cell lines." (PMID 34238324, 2021). "We found that tumor size and weight were significantly suppressed in the calpain-9 group, compared with those in the calpain-8 group and control group." (PMID 27404891, 2016). "We found that the calpain-9 mRNA expression was decreased in tumor tissues in both GEO and TCGA datasets, and also displayed the highest fold change among the members of calpain family." (PMID 27404891, 2016). "We speculated that this may be due to different mechanisms of action mediated by the CAPN9 gene in different tumors and in different stages of development of the same tumor." (PMID 34238324, 2021). "Our results show patients with an intermediate NPI had a significantly worse disease-specific survival if their tumours had low expression of calpain-9, which could be potentially examined in these patients to aid decision making on systemic treatment." (PMID 25539577, 2014). "In addition, the mutation frequencies of UNC13C, PIKfyve, and CAPN9 were significantly different between EUR and AFR (p < 0.05) and might affect prognosis by regulating tumor proliferation and apoptosis." (PMID 34950653, 2021). "PIKfyve and CAPN9 showed a significant difference in mutation frequency between EUR and AFR; PIKfyve was related to Ki-67 expression, suggesting that it could promote tumor proliferation, and CAPN9 was related to the expression of Bcl-2, promoting tumor cell apoptosis." (PMID 34950653, 2021). "Calpain-9, but not calpain-8, induced cell cycle arrest in the G1 phase and cellular apoptosis in vitro, and it attenuated the growth of subcutaneous tumor xenografts in vivo." (PMID 27404891, 2016). "Nevertheless, in transformed gastric mucosa, calpain-9, but not calpain-8, might function as a tumor suppressor through proliferation suppression and apoptosis induction." (PMID 27404891, 2016).
cancer (4 papers, 2018 to 2021). A tumor composed of atypical neoplastic, often pleomorphic cells that invade other tissues. "In contrast, calpain-9 has been found to be predominately expressed in the stomach, and altered expression of calpain-9 has been associated with poor prognosis in cancer patients and increased apoptosis." (PMID 34685571, 2021).
CAPN9 also shares sentences with these, for which no sentence is quoted: gastric tumor (1 paper); heart disease (1); laryngeal carcinoma (1); schizophrenia (1).